CXCL16 (C-X-C motif chemokine ligand 16)
Diseases named in the same sentence as CXCL16 in open-access papers (continued):
Sharing a sentence is not in itself a finding about the gene and the disease.
tumor (continued). "This study suggests that Fn infection stimulates tumor cells to produce exosomes enriched with miR-1246/92b-3p/27a-3p and CXCL16/RhoA/IL-8, which are then delivered to uninfected cells, promoting pro-metastatic behaviors." (PMID 39000577, 2024). "Functional studies in vitro and in vivo identify a specific subset of CAFs termed glycolytic cancer-associated fibroblasts (glyCAF), which rely on glycolysis to impede cytotoxic T-cell entry into the tumor mass via the Cxcl16/Cxcr6 axis." (PMID 38509063, 2024). "Commensal bacteria are important regulators of anti-tumor immunity, and gut microbiome-mediated primary-to-secondary BA conversion can regulate the accumulation of NK T cells by CXCL16 expression in liver sinusoidal endothelial cells." (PMID 39064815, 2024). "In this respect, it remains critical to decipher the contribution of myeloid-derived CXCL16 in positioning lymphocytes in the tumor microenvironment." (PMID 38509063, 2024). "In a mouse melanoma model, CXCR6 expression has been shown to result in the presence of tumor-specific CD8+ TRM cells within CXCL16+ DC clusters in the skin, ensuring the persistence and functioning of these cells." (PMID 37545498, 2023). "Chemokines such as CCL2 and CXCL16 can have direct effects on tumor cells, promoting cell motility and invasion." (PMID 37301772, 2023). "Radiation therapy enhanced CXCL16 secretion and induced the migration of NK cells toward tumor cells." (PMID 38162672, 2023). "We also determined the correlation coefficients between the studied parameters, which confirmed that the concentration of CXCL5, CXCL16 and both tumor markers are closely related to the severity of CRC." (PMID 37848726, 2023). "Intriguingly, the mean relative tumor volume significantly decreased from 4 in IgG to 1.8 with combo treatment of CXCL16 NAb and anti-PD-1 antibody compared with anti-PD-1 alone." (PMID 37055410, 2023). "Our data demonstrates that CXCL16 surface expression on TAMCs results in predominant T-cell engagement with these cells, leading to impaired T-cell function within the tumor environment." (PMID 38299146, 2023). "To examine the potential role of myeloid-derived CXCL16 in regulating tumor infiltration of bone marrow-derived immune cells (BMD cells), we performed an intratumoral CXCL16 neutralization experiment." (PMID 37055410, 2023). "These cytokines bind to receptors on NK cells and enhance immune cell migration and infiltration into the tumor site.In addition, radiotherapy-induced production of CXCL8 with CXCL16 has been reported to be associated with NK cell migration and infiltration." (PMID 38162672, 2023). "We used flow cytometry to validate how different immune cell populations express CXCL16 in CT2A tumor-bearing mice." (PMID 38299146, 2023). "Meanwhile, CXCL16 expression promotes the accumulation of tumor-specific CXCR6+CD8+ T cells in tumor tissues." (PMID 36966334, 2023). "In head-and-neck tumors, intranasal immunization induces CXCL16 production in broncho-alveolar lavage (BAL) and pulmonary parenchyma, and is associated with the formation of tumor-specific TRM cells." (PMID 37545498, 2023). "CXCL10 is a cytokine believed to promote immunosuppression and tumor stemness while CXCL16 has a beneficial effect on cancer control since it promotes lymphocyte infiltration in the tumor." (PMID 37006319, 2023). "From the immune response regulation aspect, 20 upregulated genes encoding chemokines with log2FC > 1.5 were selected, among which Ccl3, Ccl4, Cxcl9 and Cxcl16 shared with both tumor suppressive roles and effects in promotion of T cell infiltration 33–36." (PMID 37996458, 2023). "Next, to explore the impact of CXCL16 NAb on lineage dynamics of tumor-infiltrating lymphocytes (TILs), we looked into percentages of CD45.1+ progenitor-like c-KIT+LIN-, Cluster 0-like CD11bhighPD-L1high, and CD11chigh I-A-I-Ehigh DCs (gating strategy)." (PMID 37055410, 2023).
tumor (continued). "Neutralization of CXCL16, resulted in decreased tumor-infiltration of immune cells, specifically CD45+ CD11b+ PD-L1high cells, c-Kit+Lin- progenitor cells, PD-1high T cells." (PMID 37055410, 2023). "Radiation can exhibit more tumor-suppressing effects as radiation induces secretion of tumor cell intrinsic CXCL-16 that recruits TH1 and CD8+ T cells to the tumor." (PMID 36611932, 2022). "Our study revealed that SPOP can bind CXCL16 and promote its degradation, resulting in CAFs increasing the spatial distance between immune cells and tumour cells." (PMID 36042498, 2022). "In another experiment found that PTC overexpression of CXCL16 is correlated with M2 polarization and promote tumor angiogenesis." (PMID 35479325, 2022). "Animal experiments have shown that tumor-derived factors such as IL-6, CXCL16, IFNγ, TNFα, and IGFBP-3 positively regulate the expression of CD38, and high expression of CD38 can enhance the immunosuppressive and tumor-promoting capacity of MDSCs." (PMID 36119033, 2022). "CXCL16 is a chemokine that is produced on tumour cells, particularly infiltrating tumour cells, and is known to signal through the CXCR6 receptor." (PMID 36042498, 2022). "On analyzing the results, three proteins were found elevated: CXCL16, amphiregulin (a tumor progression protein), and tissue inhibitor metalloproteinases (TIMP1)." (PMID 36358879, 2022). "As a result, we show that SPOP can enhance its own degradation by binding CXCL16 and encouraging the creation of CAFs, increasing the geographical distance between T cells and tumour cells." (PMID 36042498, 2022). "It is notable that activated DCs and macrophages can secrete many types of pro-inflammatory cytokines and chemokines, such as IFN-α and CXCL16 in the tumor environment." (PMID 35959371, 2022). "In other tumor entities, CXCL16 plays a relevant role in the interaction between tumor cells and the microenvironment." (PMID 36078040, 2022). "Ionizing radiation markedly increases the production of CXC chemokine ligand 16 (CXCL16) and induces strong chemotaxis of tumor-specific CD8+ T cells." (PMID 36139006, 2022). "Upon capture of tumor antigens, antigen-presenting DCs produce CXCL16 that recruit CXCR6-expressing effector T cells in tumor tissue." (PMID 35757015, 2022). "have found that the expression of CXCL16 by the tumor cells enhances the recruitment of TILs, thereby leading to a better prognosis in CRC." (PMID 35320940, 2022). "Continuous administration of d-MAPPS increased concentration of CXCL16 in the tumor microenvironment and attracted tumoricidal, perforin, and granzyme-expressing CD8+CTLs, CD4+Th1, and Th17 lymphocytes in the tumors of 4T1+d-MAPPS-treated mice." (PMID 35757015, 2022). "Our findings demonstrated that the CXCL16 expression on LSECs induced by simvastatin attracted CXCR6+ NKT cells in the liver to inhibit tumor growth, which is consistent with previous studies." (PMID 34983554, 2022). "In an in vivo study of nude mice, high CXCL16 expression is associated with M2-macrophage infiltration in BRAFV600E mutated PTC, promoting tumor angiogenesis and resulting in poor prognosis." (PMID 35479325, 2022). "Our data showed that both culture supernatant and cell lysate of TCh3 tumor cells contained a higher level of CXCL17 and CXCL16 than those of TAb2 tumor cells, in line with our RNA-seq data." (PMID 35366939, 2022). "Intranasal vaccination induces CXCL16 production in the lungs and is associated with infiltration by TRM expressing CXCR6, which are then required for the efficacy of anti-tumor vaccination." (PMID 36311728, 2022). "The authors found that CXCL16 is involved in the viability and invasion of tumor cells, while the expression of CXCR6 by cancer cells triggers oncogenic pathways associated with cancer progression and metastasis." (PMID 36311728, 2022).
tumor (continued). "In summary, CXCL16 and its receptor play an important role in the tumour tropism of MSCs, but the biological mechanisms by which cell movement is triggered and supporting the production of energy for the MSC migration process remain to be further studied." (PMID 35869057, 2022). "Breaking CXCR6-mediated retention in the tumor by anti-CXCL16 treatment resulted in more T cells egressing to the distant lung tissue and a decrease metastatic tumor burden." (PMID 36311728, 2022). "For example, The combination of CXCL16 derived from M2-TAMs with angiogenic genes leads to high aggressiveness of PCT, and knockout of endogenous CXCL16 delayed tumor growth in athymic mice." (PMID 35479325, 2022). "CXCL16/CXCR6 signaling promotes the modulation of GAMs toward an anti-inflammatory/pro-tumor phenotype, and also restrains microglia polarization toward an inflammatory phenotype upon LPS and IFNγ stimulation." (PMID 34071306, 2021). "Newly synthesized CXCL16 is transported to the cell surface and suppresses the tumor proliferation while tethered to the membrane." (PMID 34298782, 2021). "This was further validated by confocal microscopy—within the 4T1 tumor tissues, CXCL16 was almost universally expressed on the surface of 4T1 tumor cells (best focus view)." (PMID 33979626, 2021). "After a series of cell signaling transduction, CXCL16 induced the proliferation, migration and invasion of tumor cells." (PMID 34345211, 2021). "CXCL16 expression in tumor and lymph nodes correlates with disease development, in particular tumor size, stage, grade and metastasis." (PMID 33800554, 2021). "For example, in liver cancer, sinusoidal endothelial cells were reported as primary producers of CXCL16 that recruited CXCR6+ anti-tumor NKT cells." (PMID 34503058, 2021). "The CXCL16/CXCR6 signaling axis has been reported involved in several kinds of tumor and in multiple signaling pathways in malignant cells, suggesting that CXCL16/CXCR6 axis is a critical role in tumor tumorigenesis and progression 12-14." (PMID 34345211, 2021). "This process is especially important after radiotherapy followed by increased CXCL16 expression in tumor cells." (PMID 33800554, 2021). "CXCR6 on tumor-specific T cells then engages with CXCL16 derived from the TME and facilitates T-cell retention." (PMID 34607898, 2021). "Another CXC chemokine family member, small-inducible cytokine B16/CXCL16 has recently emerged in the regulation of the anti-tumor response." (PMID 34503058, 2021). "It revealed that CXCL16 was high expressed in GC-derived tumor cell lines compared to the normal gastric mucosa-derived cell line GES-1." (PMID 34345211, 2021). "Since CXCR6 is the receptor that chemoattracts TEff/EM cells in the tumor, we predicted that its sole ligand, CXCL16, would be expressed in the tumor tissue." (PMID 33979626, 2021). "Researchers have used NK92 cells to bring drug-loaded nanoparticles to a solid tumor and block inhibitory signals in the TME, and local delivery of chemoattractants such as CCL20 or CXCL16 can increase tumor infiltration by ILCs." (PMID 33968039, 2021). "In the first step of therapy, there is an increase in the expression of CXCL16, a chemokine involved in tumor infiltration by anti-tumor TIL." (PMID 33800554, 2021). "The interaction between CXCR6-expressing TRM cells and CXCL16-expressing APCs was found to be critical for sustaining TRM cell–mediated tumor protection." (PMID 34362825, 2021). "To test this, at days 7, 14, and 21 after primary tumor inoculation, we intratumorally injected a CXCL16 antibody to neutralize CXCR6 binding." (PMID 33979626, 2021). "We reasoned that in this 4T1 model, tumor cells served as the source of CXCL16 to retain tumor-infiltrating TEff/EM cells." (PMID 33979626, 2021). "But it was reported that CXCR6 upregulated in a portion of T cells 33, 34, and these CXCR6+ T cells would be recruited to the tumor tissue by the gradient of CXCL16." (PMID 34345211, 2021).
tumor (continued). "CXCL16 also causes the survival of MDSC, which is important in the accumulation of these cells in the tumor niche." (PMID 33800554, 2021). "Our data show high expression of ligand in many tumor clusters, including high CXCL12 in Tr11, CXCL2 in Tr3, and CXCL16 in Tr10 with high CXCR4 receptor expression in tumor endothelial cells supporting prior reports." (PMID 34497364, 2021). "In our previous study, the RNA micro-array screening in GC showed CXCL16 upregulated in tumor tissue." (PMID 34345211, 2021). "To further substantiate the CXCL16 role in Trm localization, we stained for F4/80, CD103, and CXCL16 markers in endpoint tumor tissues and analyzed them using confocal immunofluorescence microscopy." (PMID 34607898, 2021). "We stained tissues from endpoint tumors from OT1+Mrb-OVA-treated mice with antibodies for mouse CXCL16 and EpCAM (tumor cell marker) and CD45 (immune cells)." (PMID 34607898, 2021). "If CXCL16 is highly expressed in a cancer cell, it increases the migration of anti-tumor lymphocytes to such cells." (PMID 33800554, 2021). "As CXCL16 attracts monocytes, it participates in the recruitment of monocytes into the tumor niche, which are then differentiated into TAM." (PMID 33800554, 2021). "CXCL16 influences the intensity of tumor cell proliferation, depending on the type of tumor as well as the form of CXCL16." (PMID 33800554, 2021). "A reduction in CXCL16 expression in A549 and PC-9 cells decreases tumor cell migration by reducing NF-κB activity." (PMID 33800554, 2021). "High expression of CXCL16 and CXCR6 promoted HCC invasiveness and a pro-tumor inflammatory environment caused by the recruitment of neutrophils." (PMID 31991677, 2020). "• CXCL16 signaling mediates the effect of macrophages on PTC tumor cell invasion and changes the macrophage phenotype to M2 TAMs in the PTC microenvironment." (PMID 33193087, 2020). "Immunohistochemistry results showed that CXCL16 was predominantly localized in the tumor stroma, whereas VEGF was expressed in tumor cells." (PMID 32163231, 2020). "Biological significance of CXCR6 and CXCL16 was tested using tumor cell migration and invasion assays." (PMID 30792527, 2019). "Strong expression of the CXCL16 protein in primary CRC tumor tissue was reported to be correlated to high numbers of tumor infiltrating T lymphocytes and a good prognosis." (PMID 31752131, 2019). "T-cell trafficking back to the tumor microenvironment is aided by radiation-induced chemokines such as C-X-C chemokine ligand 16 (CXCL16) by the tumor and intercellular (ICAM) and vascular cell adhesion molecules expression by the endothelial cells." (PMID 31788476, 2019). "Recently, several experimental studies demonstrated that CXCL16 was dominantly secreted from stromal cells such as fibroblasts and myeloid cells and supported tumor cell migration and invasion." (PMID 31527616, 2019). "The therapeutic potential of targeting CXCL16 was explored using the murine ectopic tumor model in vivo." (PMID 31527616, 2019). "In murine ectopic tumor models, CXCL16-depleted PTC cells exhibited a significantly reduced tumor growth with decreased macrophage infiltration and tumor angiogenesis." (PMID 31527616, 2019). "It suggested that CXCL16 is the essential player in TAM-enriched tumor microenvironment and can be a potent therapeutic target." (PMID 31527616, 2019). "Accordingly, immunohistochemistry analysis in mouse tumor tissues showed that sildenafil decreased stromal CXCL16 levels also ‘in vivo’." (PMID 31698786, 2019). "All these data indicate that activation of CXCL16/CXCR6 axis in human primary GBM cells is able to promote tumor cell proliferation, migration and invasion." (PMID 30542347, 2018). "Using cxcr6ko mice, we confirmed the crucial role of the CXCL16/CXCR6 axis in the establishment of a pro-tumor microenvironment." (PMID 30542347, 2018).
tumor (continued). "We were able to show now that the transmembrane chemokine CXCL16 can also mediate reverse signaling and promotes migration in the tumor context." (PMID 28698473, 2017). "In this study, we have demonstrated that co-stimulatory CXCR6/CXCL16 interactions specifically increase IFNγ production following glycolipid activation and lead to enhanced tumor control in vivo following adoptive DC transfer." (PMID 27471636, 2016). "These experiments implicate an important role for CXCR6/CXCL16 interactions in regulating iNKT cell IFNγ production and tumor control." (PMID 27471636, 2016). "In conclusion, our data demonstrate that CXCR6/CXCL16 co-stimulatory interactions between DCs and iNKT cells play an important role in mediating glycolipid-dependent tumor control." (PMID 27471636, 2016). "Both CXCR6−/− and CXCL16−/− mice exhibit enhanced tumor growth and metastasis in experimental models." (PMID 27471636, 2016). "This study examined the co-stimulatory role of CXCR6/CXCL16 interactions in glycolipid-dependent iNKT cell activation and tumor control." (PMID 27471636, 2016). "It is also noteworthy that membrane CXCL16 is expressed by a large number of organs including brain, kidney and colon during inflammation and this could be the cause of wider metastatic array of LuCa once the cells have dislodged from the original site of tumor." (PMID 25888629, 2015). "CXCL16 is a chemokine binding to its receptor CXCR6 on activated T cells therefore enhancing their recruitment to the tumor site." (PMID 26500646, 2015). "Nonetheless, differential effect of CXCL16 on MMPs possibly resulting in variations in migration and invasion capacity of cells suggests differences in mechanisms of tumor progression exploited by the two cell types." (PMID 25888629, 2015). "CXCL16 and CXCR6 are up-regulated in many cancers, and increased expression has been linked to more aggressive disease and advanced tumor stage, though few studies have shown increased expression to be independently linked to reduced survival." (PMID 26021984, 2015). "Trans-membrane CXCL16 promotes cell-cell adhesion, lymphocyte accumulation at tumor sites and leads to tumor immunity and better prognosis." (PMID 25888629, 2015). "Tumor volumes and weights for CXCL16-overexpressing groups were accordingly found to be significantly reduced (P < 0.05)." (PMID 24864132, 2014). "In conclusion, we have shown that tumor-derived CXCL16 is a key factor in colorectal liver metastasis." (PMID 25495942, 2014). "With respect to the CXCL16/CXCR6 axis, we were the first to report that CXCL16 expression by tumor cells enhances the recruitment of tumor-infiltrating lymphocytes, thereby bringing about a better prognosis for CRC patients." (PMID 25495942, 2014). "Stimulation of BM myeloid cells by crosslinking CD79a induced the secretion of several cytokines associated with tumor and metastasis promotion, in particular IL-6, RANTES, TNFR-II, CXCL16 and CCL22." (PMID 24146823, 2013). "In a third part of our study, we investigated potential roles for CXCL16 and CXCR6 on tumor-associated lymphocytes." (PMID 19690611, 2009). "We studied expression of CXCL16 in an additional 461 specimens covering 12 tumor types, and found that CXCL16 was expressed in multiple human cancers associated with inflammation." (PMID 19690611, 2009). "Mechanistically, a circuit of bile acid, CXCL16, CXCR6, and NKT cell links gut microbes to hepatic anti-tumor surveillance: microbial 7α-dehydroxylation of bile acids lowers sinusoidal CXCL16, reduces CXCR6+ NKT cell accumulation, and favors hepatocarcinogenesis." (PMID 41486167, 2026). "Interestingly, blocking CXCL16 in metastatic lung models of breast cancer redirects T-cells to distant lung tissues, reducing the metastatic tumour burden." (PMID 40361472, 2025). "Additionally, ELK3 suppresses chemotactic cytokines such as CXCL16 to inhibit tumor-infiltrating NK cells." (PMID 39930469, 2025).